UBA1 (ubiquitin like modifier activating enzyme 1)
Diseases named in the same sentence as UBA1 in open-access papers (continued):
Sharing a sentence is not in itself a finding about the gene and the disease.
VEXAS syndrome (continued). "In late 2020, partial loss-of-function mutations in UBA1 within hematopoietic stem and progenitor cells were found to be responsible for VEXAS Syndrome, a previously unidentified hematoinflammatory disorder predominantly affecting older males." (PMID 39347709, 2024). "Subsequent to its reporting, VEXAS syndrome was considered as a unifying diagnosis and a Sanger sequencing–based test demonstrated the presence of a p.Met4Leu UBA1 mutation in peripheral blood." (PMID 39411287, 2024). "VEXAS syndrome is caused by mutations in the UBA1 gene, leading to dysfunction of the ubiquitin-like-modifier-activating E1 enzyme, the most important enzyme in the ubiquitylation cascade." (PMID 39594638, 2024). "VEXAS syndrome is an inflammatory disease caused by UBA1 gene somatic mutations, which is an adult‐onset inflammatory disease with overlapping haematological manifestations." (PMID 39183260, 2024). "VEXAS syndrome, an uncommon yet severe autoimmune disorder stemming from a mutation in the UBA1 gene, is the focus of this paper." (PMID 39289602, 2024). "AZA offers significant promise, particularly with its ability to induce complete molecular clearance of UBA1 mutations, making it a promising therapeutic option for managing both the hematological and inflammatory aspects of VEXAS syndrome." (PMID 39594638, 2024). "Although the bone marrow biopsy and hematologic testing were inconclusive, genetic testing for adult-onset autoinflammatory diseases was carried out, revealing a pathogenetic UBA1 mutation c.122T > C p.(Met41Thr), confirming the diagnosis of VEXAS syndrome." (PMID 39251478, 2024). "VEXAS syndrome, a monogenic X-linked disorder resulting from mutations in the UBA1 gene, has emerged as a key model for unraveling the links between systemic inflammatory or autoimmune diseases (SIAD) and myelodysplastic syndromes (MD)." (PMID 39594638, 2024). "VEXAS Syndrome results from loss-of-function mutations in UBA1, which encodes for a critical enzyme within the ubiquitylation pathway." (PMID 39347709, 2024). "The predominant VEXAS syndrome-causing mutations identified to date occur at p.M41, the start codon for the cytoplasmic isoform of UBA1 (UBA1b)." (PMID 38360993, 2024). "VEXAS syndrome is a newly described autoinflammatory entity characterized by somatic mutations in the UBA1 X-linked gene in hematopoietic progenitor cells." (PMID 39421750, 2024). "To better understand the mutational spectrum of VEXAS syndrome, we analyzed UBA1 variants within a cohort of patients referred for genetic testing given clinical concern for severe systemic inflammatory disease." (PMID 38360993, 2024). "Due to the potential of VEXAS syndrome, genetic testing was pursued, uncovering the c.118-1G > C mutation in the UBA1 gene." (PMID 39251478, 2024). "A growing number of studies have identified the cooccurrence of UBA1 mutations with other mutations in patients with VEXAS syndrome." (PMID 37501758, 2023). "In order to rule out any possible bias, we initially performed a mutational screening analysis for the UBA1 gene, the pathognomonic alteration recently associated with VEXAS syndrome." (PMID 37507570, 2023). "The underlying diagnosis of VEXAS syndrome was confirmed by genetic testing, which revealed the UBA1 mutation." (PMID 37673972, 2023). "In a VEXAS syndrome cohort, the dominant disease-causing variant was found to be the p.Met41Thr variant of the UBA1 gene." (PMID 36879894, 2023). "In VEXAS syndrome, a somatic mutation (acquired later in life) in UBA1 in hematopoietic progenitor cells leads to reduced cytoplasmic expression of E1 activating enzyme." (PMID 37673972, 2023). "A pathogenic variant of UBA1, which is the cause of VEXAS syndrome, was identified by CES from a 64-year-old male patient (Case 15)." (PMID 37325673, 2023). "DNA analysis from bone marrow revealed a mutation in UBA1, confirming the diagnosis of VEXAS syndrome." (PMID 37673972, 2023).
VEXAS syndrome (continued). "VEXAS syndrome is a recently described disease entity caused by somatic mutation in the UBA1 coding gene, localized on the X-chromosome." (PMID 36879894, 2023). "In VEXAS syndrome, both aberrant inflammation and myeloid predominance appear intrinsic to hematopoietic stem cells mutated in UBA1." (PMID 37586319, 2023). "Our data strongly favor UBA1 mutations in HSPCs as immediate drivers of both myeloid lineage dominance and the origin of inflammation in VEXAS syndrome." (PMID 37586319, 2023). "Through paired sequencing analysis, it has been demonstrated that the dermal infiltrates in VEXAS syndrome derive from the same pathological UBA1-mutated myeloid clone found in the bone marrow." (PMID 36662445, 2023). "VEXAS syndrome is caused by somatic postzygotic mutations of the UBA1 gene located on chromosome Xp11.23." (PMID 36662445, 2023). "Specifically, UBA1 hypomorphic mutations cause VEXAS syndrome, an adult-onset systemic inflammatory condition that leads to progressive bone marrow failure because of defects in the function of hematopoietic stem cells." (PMID 37963875, 2023). "Rare somatic variants in UBA1 were previously demonstrated to be pathogenic for VEXAS syndrome, a monogenic disease with a large degree of clinical overlap with RP." (PMID 37292664, 2023). "Based on the current understanding of the pathophysiological mechanisms of VEXAS syndrome, two therapeutic strategies have been proposed: eradicating UBA1 mutations and blocking the inflammatory cascade response." (PMID 37501758, 2023). "VEXAS syndrome is an autoinflammatory disease of myeloid origin resulting from somatic mutations in the UBA1 gene." (PMID 37507570, 2023). "Sequencing of UBA1 confirmed mosaicism for the known pathogenic missense variant p.Met41Thr in UBA1, thus confirming VEXAS syndrome." (PMID 36879894, 2023). "Given the identification of potential novel UBA1 variants causing VEXAS syndrome outside of the M41 codon, we went on to analyze WGTS of 4168 patients (see “Material and Methods”) with a broad range of myeloid and lymphoid malignancies." (PMID 36823397, 2023). "Sanger sequencing of UBA1 was performed using genomic DNA from peripheral blood leukocytes and revealed a somatic variant (c.122T>C:p.Met41Thr) consistent with VEXAS syndrome." (PMID 35757758, 2022). "All cases described in the literature corroborate that UBA1 variants associated with VEXAS syndrome are found in somatic cells and affects predominantly males, with only 4 female cases reported, all related to monosomy X." (PMID 36038944, 2022). "In previous reports of VEXAS syndrome, the UBA1 variant was found only in neutrophilic dermatitis by skin biopsy, and not in leukocytoclastic vasculitis or septal panniculitis." (PMID 36544501, 2022). "We describe the clinical course of a VEXAS syndrome patient with a somatic UBA1 variant who was treated with an oral steroid and anti-IL-6 therapy (tocilizumab) that lead to the resolution of the systemic symptoms." (PMID 36544501, 2022). "In our case of VEXAS syndrome with a somatic UBA1 variant (p.Met41Thr), the typical pathological findings of MM without myeloid dysplastic changes were demonstrated." (PMID 35757758, 2022). "We report on an individual with the phenotype of VEXAS syndrome initially identified as having an apparent hemizygous germline variant in UBA1 due to high variant allele frequency (VAF) in a clinical exome sequencing (ES)." (PMID 36038944, 2022). "VEXAS syndrome is caused by pathogenic variants in ubiquitin-like modifier activating enzyme 1 (UBA1), a gene on the X chromosome that encodes UBA1, and these mutations are restricted to myeloid-lineage cells." (PMID 36544501, 2022). "In the present case of coexisting auricular chondritis and MM, a somatic variant in UBA1 (c.122T>C) resulted in amino acid substitution at codon 41 (p.Met41Thr), which has previously been reported in patients with VEXAS syndrome." (PMID 35757758, 2022).
VEXAS syndrome (continued). "We report a male individual with the phenotype of VEXAS syndrome that was initially identified through exome sequencing (ES) as having a hemizygous germline variant in UBA1 due to high variant allele frequency (VAF)." (PMID 36038944, 2022). "In the initial report, 25 patients were diagnosed with VEXAS syndrome based on the confirmation of somatic mutations in codon 41 of UBA1 (p.Met41Val, p.Met41Thr, or p.Met41Leu)." (PMID 36045928, 2022). "VEXAS syndrome is a very recently identified autoinflammatory disorder caused by acquired somatic mutations of UBA1 gene in blood cells precursors." (PMID 35899212, 2022). "VEXAS syndrome is a recently identified disease characterized by systemic inflammation and progressive BM cell dysplasia caused by the somatic UBA1 variants in hematopoietic cells." (PMID 35757758, 2022). "Genomic DNA from peripheral blood leukocytes was subjected to Sanger sequencing and peptide nucleic acid-clamping PCR of UBA1, identifying a somatic variant (NM_003334.3:c.122T>C:p.Met41Thr) that strongly supported the diagnosis of VEXAS syndrome." (PMID 35757758, 2022). "VEXAS syndrome is caused by UBA1 variants in myeloid lineage cells, including neutrophils and macrophages." (PMID 36544501, 2022). "VEXAS syndrome is caused by somatic mutations of the ubiquitin-like modifier activating enzyme 1 (UBA1) gene in myeloid-lineage cells." (PMID 36544501, 2022). "UBA1 mutations are rare but have gained recognition due to their association with VEXAS syndrome." (PMID 41419605, 2026). "However, to make a definitive diagnosis of VEXAS syndrome, the presence of the UBA1 gene mutation is mandatory." (PMID 41246582, 2025). "VEXAS syndrome is a recently identified adult‐onset disease caused by somatic mutations in UBA1." (PMID 41347012, 2025). "One hypothesis for how UBA1 mutations cause VEXAS syndrome is that the mutations lead to the activation of the unfolded protein response (UPR) and multiple inflammatory pathways." (PMID 39982357, 2025). "The identification of the UBA1 mutation through next-generation sequencing, along with characteristic hematologic findings such as cytopenias and vacuolization, and evidence of multi-organ inflammatory involvement, confirmed the diagnosis of VEXAS syndrome." (PMID 40600106, 2025). "VEXAS syndrome (Vacuoles, E1 enzyme, X-linked, Autoinflammatory, Somatic) is an adult-onset autoinflammatory disorder caused by somatic loss-of-function mutations in the UBA1 gene within hematopoietic progenitor cells." (PMID 41409287, 2025). "In a VEXAS syndrome model using a myeloid cell line engineered with a UBA1 Met41euL mutation, TAK-243 treatment led to preferential apoptosis and loss of the UBA1-mutant cells compared to wild-type, indicating that reduced UBA1 activity renders cells uniquely vulnerable to UBA1 inhibition." (PMID 40791602, 2025). "VEXAS syndrome is a recently recognized CH‐related condition that is characterized by progressive systemic autoinflammatory manifestations, vacuoles in myeloid/erythroid precursors in the bone marrow, and somatic mutations in the X‐linked gene UBA1." (PMID 39403025, 2025). "Targeted sequencing of the UBA1 gene has proven to be a highly sensitive and efficient diagnostic tool for identifying pathogenic variants responsible for the clinical phenotype associated with VEXAS syndrome." (PMID 40869252, 2025). "Patient studies have hinted that the transition of UBA1-mutated stem cells into proinflammatory myeloid precursors may propagate the manifestations of VEXAS syndrome." (PMID 41178709, 2025). "Notably, The UBA1 c.118-1G>C splice-site mutation found in our patient is extremely rare in VEXAS syndrome." (PMID 41394827, 2025). "The underlying pathogenesis of VEXAS syndrome is UBA1 mutations in hematopoietic stem cells and myeloid-lineage cells, by substitution of methionine-41 (pMEt41), consequently decreasing the breakdown of proteins, disruption of cell homeostasis, and increased endoplasmic reticulum stress." (PMID 38410307, 2024).
VEXAS syndrome (continued). "VEXAS syndrome is characterized by an acquired inactivating mutations in the X-linked UBA1 gene." (PMID 39168911, 2024). "UBA1 is a known orchestrator of DNA damage response, and coinciding with the discovery of VEXAS syndrome, UBA1 mutations were implicated as potential key factors in the development of lung cancer among non-smokers, identified through advanced bioinformatics methods." (PMID 39347709, 2024). "Somatic mutation of UBA1 gene is the genetic basis of VEXAS syndrome." (PMID 38167209, 2024). "VEXAS syndrome is a rare condition characterized by somatic mutations in the ubiquitin‐like modifier activating enzyme 1 (UBA1) gene and a constellation of clinical/morphologic findings, including the presence of cytoplasmic vacuoles within bone marrow hematopoietic cells." (PMID 39415928, 2024). "Genetic analysis by bidirectional Sanger sequencing and capillary electrophoresis showed pathogenic missense SNV c.121A>C (p.Met 41Leu) in exon 3 of X-linked UBA1 (NM_003334.4) gene along with the wild-type allele in peripheral blood and bone marrow samples; confirmed diagnosis of VEXAS Syndrome." (PMID 39463879, 2024). "One study identified Vexas syndrome as a myeloid-driven inflammatory disorder caused by somatic mutations in the UBA1 gene, further exposing the increasingly recognized overlap between hematologic disorders and autoimmune and/or autoinflammatory manifestations." (PMID 38165493, 2024). "These molecular insights provide a framework for studying regulatory principles of ubiquitylation at the E1-E2 level, for determining cellular downstream consequences of loss of UBA1 activity, and for developing therapeutic strategies to treat VEXAS syndrome and UBA1-related diseases in the future." (PMID 38360993, 2024). "Age might also play a role in VEXAS syndrome, as evidenced by the identification of several younger, asymptomatic patients carrying the UBA1 M41 mutations, who exhibited lower VAFs." (PMID 39347709, 2024). "This revealed the p.Met41Leu mutation in the UBA1 gene, confirming suspicions of VEXAS syndrome." (PMID 39251478, 2024). "VEXAS syndrome, an infrequent and grave autoimmune malady arising from a UBA1 gene mutation." (PMID 39289602, 2024). "Interestingly, the diagnostic marker for VEXAS syndrome, UBA1 M41T mutation (VAF, 83.3%), was identified in a 38-year-old male patient, and we reviewed his clinical disease course." (PMID 38137719, 2023). "A UBA1 M41T mutation that causes VEXAS syndrome was identified in a male patient." (PMID 38137719, 2023). "Moreover, we identified a somatic UBA1 mutation, which was the underlying cause of VEXAS syndrome (Vacuoles, E1 enzyme, X-linked, Autoinflammatory, Somatic), in one patient." (PMID 38137719, 2023). "However, VEXAS syndrome can be confirmed only by the presence of a somatic UBA1 variant, usually in peripheral blood." (PMID 36544501, 2022). "Therefore, somatic mutations found in VEXAS syndrome lead to a reduction in cytoplasmic UBA1 function, and the resultant decreased ubiquitylation activates the unfolded protein response and type I interferon production." (PMID 36045928, 2022). "Furthermore, it is essential to describe the UBA1 mutations really capable of determining VEXAS syndrome, highlighting pathogenic or likely pathogenic variants from benign polymorphisms." (PMID 35899212, 2022). "Finally, genetic testing for UBA1 mutation confirmed the diagnosis of VEXAS syndrome." (PMID 41646962, 2026). "Epidemiologic studies suggest that pathogenic and likely pathogenic UBA1 variants are more common than expected, with prevalence estimates near 1 in 4,000 men older than 50 years, albeit with evidence of incomplete clinical penetrance of VEXAS syndrome–associated UBA1 variants." (PMID 41178709, 2025).
VEXAS syndrome (continued). "For patients with suspected somatic mosaicism leading to disease, for example, suspected VEXAS syndrome, clinical testing may need to be targeted to the potential genes causing disease, and UBA1 (the gene associated with VEXAS) is now on many clinical deep-sequencing panels." (PMID 40842819, 2025). "A germline pathogenic variant in the same UBA1 gene leads to a syndrome with far higher incidence of severe neurological features than its VEXAS syndrome somatic sister—X-Linked Spinal Muscular Atrophy 2 (SMAX2)." (PMID 40650768, 2025). "However, the presence of the UBA1 mutation is a hallmark of VEXAS syndrome in all patients." (PMID 40041629, 2025). "Similarly, VEXAS syndrome only arises in males who carry a somatic LOF variant in the UBA1 gene." (PMID 39762237, 2025). "Using lineage-specific Cre drivers, they ablated Uba1 in HSCs, lymphoid cell subsets, monocytes/macrophages, megakaryocytes, and neutrophils, thereby directly interrogating which cellular subsets are most closely linked to the autoinflammation observed in VEXAS syndrome." (PMID 41178709, 2025). "In addition, recent reports, including ours, suggest that mutations at other sites than p.Met41 can cause VEXAS syndrome, highlighting the existence of disease mechanisms distinct from the canonical loss of cytoplasmic UBA1 activity, but molecular details have remained elusive." (PMID 38360993, 2024). "Indeed, the low frequency of RA developing into AML may in some cases be associated with certain somatic mutations, such as UBA1 in Vexas syndrome." (PMID 38165493, 2024). "The UBA1 somatic variant was detected from a patient with a long history of recurrent infections and systemic inflammation of unknown etiology, whose diagnosis of VEXAS syndrome was made by CES." (PMID 37325673, 2023). "Interestingly, AF potently enhanced gp78-catalyzed ubiquitination in the presence of the cytosolic form of UBA1, UBA1b, or the VEXAS syndrome-causing UBA1c, a truncated form of UBA1b that uses methionine 67 as translation start codon due to mutations of codon methionine 4115." (PMID 37558718, 2023). "Having VEXAS syndrome in mind, genetic testing identifying the UBA1 gene mutation was performed, thus confirming our suspicion." (PMID 36879894, 2023). "For the development of VEXAS syndrome and acquisition of the UBA1 mutation in patients with JAK2V617F mutation or other driver mutations, it is currently unknown when the time course of these events occurs in relation to the development of fulminant phenotypic disease." (PMID 36879894, 2023). "VEXAS syndrome (vacuoles, E1 enzyme, X-linked, autoinflammatory, somatic syndrome) is a recently described syndrome caused by a somatic missense variant at the methionine-41 (p.(Met41)) position in the ubiquitin-like modifier activating enzyme 1 (UBA1) in Xp11.3." (PMID 36038944, 2022). "This convergence of age-related proteostasis decline and UBA1 insufficiency therefore provides a mechanistic basis for the persistent, cytokine-amplified inflammation that typifies VEXAS syndrome in older adults." (PMID 40791602, 2025). "Together, these data support a model in which the clonal expansion of UBA1-mutant hematopoietic stem cells (HSCs) gives rise to dysfunctional, myeloid-skewed progeny that propagate inflammation in VEXAS syndrome." (PMID 41178709, 2025). "Pathogenic and likely pathogenic mutations associated with VEXAS syndrome cluster at the methionine-41 codon of UBA1, selectively reducing the expression of the cytoplasmic UBA1b isoform, while sparing nuclear UBA1a." (PMID 41178709, 2025). "Whole-exome sequencing identified a somatic UBA1 splice-site mutation (c.118-1G>C; ClinVar VCV001298353.3, Pathogenic), suggesting the possibility of VEXAS syndrome." (PMID 41394827, 2025). "In this issue of the JCI, Dong and colleagues developed nine unique conditional knockout mouse strains and found that only neutrophil-specific Uba1 deletion reproduced VEXAS syndrome–like findings." (PMID 41178709, 2025).